MEI1 (meiotic double-stranded break formation protein 1)
Description:
Required for normal meiotic chromosome synapsis. May be involved in the formation of meiotic double-strand breaks (DSBs) in spermatocytes (By similarity).
Synonyms: MGC40042; SPATA38; HYDM3
Tractability: No criterion of Open Targets' tractability assessment is met for any kind of drug.
Gene: Protein-coding gene on chromosome 22 (41,699,503 to 41,799,456, forward strand). Ensembl gene ENSG00000167077.
Gene Ontology:
Biological process: meiosis I
Genetic constraint (gnomAD): Loss-of-function variants: 86 observed, 120.63 expected, observed/expected ratio (o/e) 0.71, 90% interval 0.6 to 0.85. The upper end of that interval is the gene's LOEUF score, 0.85, which puts it in group 3 of 6, group 1 being the genes least tolerant of losing a copy. Missense variants: 1,454 observed, 1,489.5 expected, observed/expected ratio (o/e) 0.98, 90% interval 0.93 to 1.02. Synonymous variants: 629 observed, 617.4 expected, observed/expected ratio (o/e) 1.02, 90% interval 0.95 to 1.09.
Homologues: Orthologues: chimpanzee MEI1 (99% identical), dog MEI1 (87% identical), rabbit MEI1 (84% identical), pig MEI1 (82% identical), mouse Mei1 (80% identical), rat Mei1 (79% identical), tropical clawed frog MEI1 (43% identical), macaque MEI1 (33% identical). Paralogues in human: BCL2L11 (5% identical), SCIMP (2% identical).
Diseases named in the same sentence as MEI1 in open-access papers:
MEI1 is named in the same sentence as 14 diseases in open-access papers, as found by Europe PMC text mining. Sharing a sentence is not in itself a finding about the gene and the disease. The quoted sentences say what the papers report.
Azoospermia (6 papers, 2022 to 2025). Absence of any measurable level of sperm,whereby spermatozoa cannot be observed even after centrifugation of the semen pellet. "Of which, MEI1 is involved in the regulation of meiosis, and its variation can lead to oocyte developmental disorders and azoospermia." (PMID 38336605, 2024). "Polymorphic alleles of MEI1 have been linked to human azoospermia, a medical condition characterized by the absence of sperm in the ejaculate due to meiotic arrest." (PMID 40070201, 2025). "MEI1 variants (including frameshifts, non-senses, and missenses) have been previously associated with non-obstructive azoospermia in male patients." (PMID 37234866, 2023). "Next-generation sequencing has contributed to the identification of several unknown genetic alterations in the context of male infertility and azoospermia including FANCA, PLK4, WKN3, MEI1, ADAD2, and TEX11." (PMID 40747475, 2025).
Infertility (3 papers, 2022 to 2026). "We applied this framework to generate gene-specific protocols for two men in whom infertility was caused by the respective disruption of the genes MEI1 and DNAH17." (PMID 41863311, 2026). "Although its specific biochemical function remains unclear, MEI1 is required for meiotic DSB formation in mice and A. thaliana and mutations in human MEI1 are associated with infertility." (PMID 41292753, 2025).
female infertility (2 papers, 2022). Diminished or absent ability of a female to achieve conception. "Moreover, we will add newly found female infertility pathogenic genes such as MEI1 and FBXO43." (PMID 35620457, 2022).
hydatidiform mole (2 papers, 2021 to 2025). A gestational trophoblastic disorder characterized by marked enlargement of the chorionic villi, hyperplasia of the villous trophoblastic cells and hydropic changes. "Recent studies have found biallelic variants of MEI1 and SPO11 in males with familial nonobstructive azoospermia, and variants of TOROVIBL, MEI1, and REC114 in females with recurrent miscarriage and hydatidiform moles." (PMID 34257419, 2021).
cervical cancer (1 paper, 2020). A primary or metastatic malignant neoplasm involving the cervix. "Similarly, patients with higher expression levels of MEI1 have better OS than those with lower expression levels in cervical cancer." (PMID 33038770, 2020).
gestational trophoblastic neoplasm (1 paper, 2024). A diverse group of pregnancy-related tumors characterized by excessive proliferation of trophoblasts. "MEI1, presumed to be involved in meiosis I, is linked to gestational trophoblastic neoplasms." (PMID 38278930, 2024).
hypogonadism (1 paper, 2010). A disorder characterized by decreased function of the gonads. "Mei1−/− mice, which harbor a frame-shift mutation that produces a truncated Mei1 mRNA, show hypogonadism with decreased gonad weight." (PMID 24710101, 2010).
sterility (1 paper, 2026). "Previous research on MEI1 primarily focused on meiosis‐induced sterility." (PMID 41467897, 2026).
viral infection (1 paper, 2025). "The results showed that the efficiency of viral infection was the highest after 72 h, being at approximately 80% for MEI1 (MXE) in pGWLV12(mcherry) and 60% MEI1 (SE) in pGWLV10-BFP." (PMID 41375492, 2025).
MEI1 also shares sentences with these, for which no sentence is quoted: acute kidney injury (1 paper); cancer (1); chronic kidney disease (1); depression (1); male infertility (1).